EGFR (epidermal growth factor receptor)
Diseases named in the same sentence as EGFR in open-access papers (continued):
Sharing a sentence is not in itself a finding about the gene and the disease.
lung adenocarcinoma (continued). "Our interest in this case arose from the fact that this case is the first report of a durable, dramatic response to alectinib in a lung adenocarcinoma patient harboring both an EGFR mutation and an ALK rearrangement for the uncommon genomic breakpoint." (PMID 36107507, 2022). "Histological subtypes, including minor components, should be considered when evaluating the risk of recurrence in patients with EGFR-mutated lung adenocarcinoma." (PMID 35266536, 2022). "This study aimed to evaluate the prognostic impact of the combination of EGFR mutations and the presence of high-grade patterns in completely resected stage I lung adenocarcinomas." (PMID 35266536, 2022). "On the one hand, a prospective, multinational, epidemiological study has shown that approximately 51.4% of Asian lung adenocarcinoma patients were with the epidermal growth factor receptor (EGFR) activating mutations." (PMID 35872868, 2022). "PPI use reduced OS and TTNT among patients with EGFR mutation-positive lung adenocarcinoma who received first-line gefitinib or erlotinib compared with those under H2RA or non-AS users." (PMID 35488047, 2022). "Tyrosine kinase inhibitors (TKIs) are the first-line treatment for patients with advanced epidermal growth factor receptor (EGFR)-mutated lung adenocarcinoma." (PMID 35053473, 2022). "Genetic analysis showed that mutation of epidermal growth factor receptor (EGFR) was the core signaling pathway in the development of GGN toward lung adenocarcinoma." (PMID 36059824, 2022). "These attention areas were inferred to be strongly related to EGFR mutation status by the deep learning model for a lung adenocarcinoma manifesting as a pGGN." (PMID 36119545, 2022). "Another study showed that a CXCR4 antagonist significantly suppressed acquired resistance to gefitinib in a lung adenocarcinoma cell line harboring EGFR mutations." (PMID 35729596, 2022). "Radiomics analysis of 18F-FDG PET/CT can predict the status of TERTp-mutation status of high-grade gliomas, EGFR mutation in lung adenocarcinoma, hormone receptor distribution, proliferation rate, lymph node and distant metastasis of breast carcinoma." (PMID 35204353, 2022). "Novel biomarkers or therapeutics are needed to predict NSCLC prognosis and enhance the efficacy of ICIs in NSCLC patients harboring EGFR mutations, especially lung adenocarcinoma (LUAD) patients, who account for approximately 40–50% of all NSCLC cases." (PMID 36229854, 2022). "High-risk human papillomavirus (HPV) infections and epidermal growth factor receptor (EGFR) expression have been reported to be associated with more favorable survival outcomes in lung adenocarcinoma patients." (PMID 36358752, 2022). "Among the top genes annotated to DMPs identified in our elastic-net models, only the gene EGFR was present in the GWAS Catalog, associated with lung adenocarcinoma." (PMID 35681244, 2022). "Systemic inflammation index and tumor glycolytic heterogeneity have independent prognostic values for survival outcomes in patients with advanced EGFR-mutated lung adenocarcinoma treated with TKIs." (PMID 35053473, 2022). "We observed that exosomes isolated from patients with EGFR-mutated lung adenocarcinoma promoted extracellular matrix degradation and a significantly increased expression of vimentin in recipient A549 cells." (PMID 35954442, 2022). "With such clinical conditions, EGFR mutation prediction using a noninvasive method such as imaging of lung adenocarcinoma manifesting as pGGN is desirable." (PMID 36119545, 2022).
lung adenocarcinoma (continued). "Recently, a phase II clinical trial evaluating the efficacy and safety of neoadjuvant osimertinib (80 mg QD for 6 weeks) for resectable EGFR-mutated lung adenocarcinoma (NEOS study) updated its findings at the 2022 ELCC meeting." (PMID 35571073, 2022). "The study conducted in China with 747 patients showed a slightly higher mutation with an overall EGFR mutation rate of 50% vs active EGFR mutation rate of 48% among their stage IIIb/IV lung adenocarcinoma patients." (PMID 35004079, 2022). "We compared the frequency of several of EGFR mutation types in lung adenocarcinoma in our research, including total EGFR mutations, EGFR sensitizing mutations, T790M mutation and exon 20 insertion, to that in the prospective MSKCC cohort." (PMID 35265073, 2022). "The purpose of this report is to propose a method for the clinical management of T790M mutation positive SQ transformation from EGFR-mutated lung adenocarcinoma through our patient." (PMID 35960133, 2022). "The results of this study confirmed the reliability of radiomic and deep learning models for the non-invasive prediction of EGFR mutation status in lung adenocarcinoma with a high degree of accuracy." (PMID 35186727, 2022). "With the discovery and development of tyrosine kinase inhibitors (TKIs), the clinical treatment strategy for advanced activating EGFR mutation lung adenocarcinoma has evolved into a personalized approach." (PMID 36052262, 2022). "The levels of several other tumor markers, including serum CA19-9, CA24-2, and cytologic CYFRA were significantly associated with EGFR mutations in NSCLC or lung adenocarcinoma." (PMID 35624472, 2022). "EGFR mutations in lung adenocarcinoma are known to occur in 10–50% of NSCLC depending on the population, tending to occur more often in females, Asians, and never smokers." (PMID 35448189, 2022). "EGFR Q787Q polymorphism was associated with better survival in patients with stage IV lung adenocarcinoma treated with TKIs." (PMID 35387120, 2022). "Patients with advanced epidermal growth factor receptor (EGFR)-mutated lung adenocarcinoma have been known to respond to first-line tyrosine kinase inhibitor (TKI) treatment." (PMID 35053473, 2022). "Survival analysis studies by this group have shown that higher expression of hTid-1L and lower expression of EGFR are associated with increased survival possibility of patients with lung adenocarcinoma." (PMID 35854300, 2022). "In the untreated EGFR‐mutated lung adenocarcinomas (LuADs), RB1 is excessively altered by inactivation, mainly through complex intragenic rearrangements." (PMID 34799997, 2022). "Among them, the CT/TT genetic polymorphism has poor cellular differentiation of cervical cancer, and a higher risk of developing EGFR mutation, advanced stage, and lymph node metastasis in lung adenocarcinoma." (PMID 36612628, 2022). "There are significant differences in the frequency of EGFR mutations, with about 10% in cases of lung adenocarcinoma in Caucasians, but about 50% in cases of lung adenocarcinoma in East Asians." (PMID 34904383, 2022). "The frequency of EGFR mutation among the Iranian population with lung adenocarcinoma referred to a specialized lung disease hospital is 19.8%, and it is higher among female patients than males." (PMID 35463723, 2022). "Approximately 30% of the patients with lung adenocarcinoma in Eastern Asia are EGFR mutation-positive." (PMID 36581856, 2022). "In this study, we combined clinical factors and radiomic features based on contrast-enhanced CT images to predict acquired T790M mutation and survival in advanced lung adenocarcinoma patients with progression after first-line EGFR TKI–targeted therapy." (PMID 35875167, 2022). "Patients who underwent curative resection for pathological stage I lung adenocarcinoma and EGFR mutation analysis were included in this study." (PMID 35266536, 2022).
lung adenocarcinoma (continued). "Epidermal growth factor receptor (EGFR) mutations were frequently found with concomitant genetic alterations in lung adenocarcinoma (LUAD)." (PMID 35023616, 2022). "Applied in 30 lung adenocarcinoma patients harboring epidermal growth factor receptor (EGFR) mutations, the system isolated diverse phenotypes of CTCs in marker expression and size, implying the importance of unbiased isolation." (PMID 35664056, 2022). "In the present study, 61 patients were diagnosed with lung adenocarcinoma, of whom 16 had EGFR mutations and 15 were treated with EGFR-TKIs." (PMID 36230708, 2022). "The patient in our report was diagnosed with stage IA lung adenocarcinoma harboring the EGFR L858R mutation and underwent radical surgery." (PMID 35872785, 2022). "Nine patients with EGFR-mutated lung adenocarcinoma who transformed to SCLC were evaluated at City of Hope." (PMID 35268520, 2022). "EGFR mutations play a crucial role in the pathogenesis of lung adenocarcinoma and affect the ability of targeted therapies to improve patient prognoses." (PMID 36675990, 2022). "Our data indicated the presence of several race-dominant molecular signatures in lung adenocarcinomas beyond EGFR mutation." (PMID 36248982, 2022). "The effective rate of treatment with TKI in patients with EGFR-sensitive mutations is up to 70%, and EGFR-TKI are the main treatments for advanced lung adenocarcinoma (LUAD)." (PMID 36675677, 2022). "Meanwhile, the ﻿combination of chemotherapy and gefitinib also provided a better survival benefit than gefitinib monotherapy for patients with lung adenocarcinoma harboring EGFR mutations by first using cytotoxic drug on day 1 and gefitinib from day 5–21." (PMID 35501907, 2022). "The study included 136 patients with tissue biopsy-confirmed EGFR-sensitizing, mutation-positive lung adenocarcinoma with plasma collected prior to TKI treatment and at least two post-initiation TKI treatment/follow-up blood samples." (PMID 35482671, 2022). "Previous studies have reported the involvement of B3GNT3 in tumorigenesis and that B3GNT3 is strongly associated with PD-L1 expression and EGFR mutation status in lung adenocarcinoma." (PMID 36613882, 2022). "Choe et al8 developed a model using both intra- and peritumoral radiomics to predict EGFR mutations in lung adenocarcinoma." (PMID 36115683, 2022). "The largest case series comprises six cases of lung adenocarcinomas (five with classic EGFR mutations and one with a ROS1 rearrangement) that underwent a sarcomatoid transformation." (PMID 35456982, 2022). "In lung adenocarcinoma, cancer-specific allocations consisted exclusively of epidermal growth factor receptor (EGFR) mutations." (PMID 35849877, 2022). "The presence of EGFR gene mutations in lung adenocarcinoma is a powerful predictor of better prognosis after gefitinib therapy." (PMID 35515138, 2022). "Gene mutation analysis detected different positive rates of EGFR ex19del in lung adenocarcinoma before and after erlotinib administration." (PMID 36505794, 2022). "The two common EGFR mutations that influence the clinical characteristics of lung adenocarcinoma are the L858R expression and exon 19 in-frame deletion." (PMID 36011604, 2022). "The clinical characteristics and prognostic factors of patients with EGFR mutated lung adenocarcinoma of different molecular subtypes combined with pleural effusion at initial diagnosis are still unclear." (PMID 35340158, 2022). "Epidermal growth factor receptor (EGFR) gene mutations are the most common driver gene alterations in Asian patients with lung adenocarcinoma, with an overall mutation frequency of 51.4%." (PMID 35990690, 2022). "Targeted tyrosine kinase inhibitors (TKIs) have been introduced as a first-line regimen for the treatment of advanced EGFR-mutated lung adenocarcinoma." (PMID 35053473, 2022). "Given the favorable efficacy, EGFR-TKIs have been recommended as standard therapy for advanced lung adenocarcinomas with common EGFR mutations." (PMID 36568152, 2022).
lung adenocarcinoma (continued). "In our study, EGFR mutation was significantly associated with poor RFS of stage I lung adenocarcinoma only in cases with high-grade patterns." (PMID 35266536, 2022). "Regardless of clinical characteristics, guidelines recommend that all advanced lung adenocarcinoma patients should be tested for EGFR mutations." (PMID 35209919, 2022). "This study aimed to noninvasively predict the mutation status of epidermal growth factor receptor (EGFR) molecular subtype in lung adenocarcinoma based on CT radiomics features." (PMID 35574401, 2022). "Lung adenocarcinoma, especially with activating EGFR mutations, has better survival outcome among patients with unresectable NSCLC." (PMID 35223474, 2022). "Previous studies related to our study mainly focused on primary lesions of lung adenocarcinoma and highlighted that radiomics can be helpful in predicting EGFR mutations and subtypes mainly from medical imaging." (PMID 35964032, 2022). "Their results show that this method can precisely recognize EGFR mutation status of lung adenocarcinoma patients." (PMID 35719907, 2022). "The patient was diagnosed with stage IVA lung adenocarcinoma with an exceptionally uncommon EGFR T854A mutation in exon 21 was detected concomitantly with EGFR T790M in blood by next-generation sequencing (NGS)." (PMID 36626541, 2022). "Our study demonstrated that a high TMB level was independently associated with poor PFS and OS in patients with EGFR-mutated lung adenocarcinoma that were treated with frontline targeted therapy." (PMID 36140210, 2022). "Here, we also showed a higher prevalence of the EGFR Q787Q polymorphism in stage IV lung adenocarcinoma than that in the general population (OR= 1.44, p=0.004), especially in wild-type EGFR cases." (PMID 35387120, 2022). "EGFR is the most prevalent targeted mutation in lung adenocarcinoma, and four FDA-approved tyrosine kinase inhibitors (TKIs) are currently in use." (PMID 36033482, 2022). "Identifying an epidermal growth factor receptor (EGFR) mutation is important because EGFR tyrosine kinase inhibitors are the first-line treatment of choice for patients with EGFR mutation-positive lung adenocarcinomas (LUAC)." (PMID 35578691, 2022). "EGFR amplification has been associated with significantly poorer outcomes in lung adenocarcinoma patients." (PMID 35978803, 2022). "The mutational EGFR status of a patient facilitated a diagnosis of lung adenocarcinoma metastasis, resulting in targeted treatment with erlotinib or gefitinib (EGFR inhibitor) and consequently disease remission." (PMID 35328664, 2022). "Cytoplasmic ERβ has been found to be involved in the development of resistance to EGFR-TKIs in patients with lung adenocarcinoma and relevant EGFR mutations." (PMID 35565393, 2022). "EGFR is the most common driver mutation in lung adenocarcinoma, with an incidence of 37.3% in China." (PMID 35151318, 2022). "We have applied this calibration strategy to a mechanistic multiscale KBM of lung adenocarcinoma harboring specific EGFR mutations, and focused on the calibration of tumor growth parameters based on in vitro experiments and xenografted mice." (PMID 35796890, 2022). "Patients with EGFR mutation-positive lung adenocarcinoma have approximately an 80% response rate to EGFR-TKIs, achieving progression-free survival of 10–14 months." (PMID 35402377, 2022). "The prevalence of EGFR mutations in lung adenocarcinoma (LUAD) can considerably change concerning the population analysed." (PMID 35454856, 2022). "EGFR Q787Q polymorphism had significant protective effects on the overall survival of EGFR-mutant lung adenocarcinoma treated with EGFR TKIs (aHR =0.61, p=0.03)." (PMID 35387120, 2022).
lung adenocarcinoma (continued). "Epidermal growth factor receptor (EGFR) mutations mainly occur in patients with lung adenocarcinoma." (PMID 35340158, 2022). "The combination of EGFR mutation and the presence of high-grade patterns was associated with recurrence in resected stage I lung adenocarcinoma." (PMID 35266536, 2022). "The intrinsic relationship between the radiomics features and EGFR mutation status in patients with lung adenocarcinoma can be further explored through data mining to guide clinical decision-making, predict prognosis and evaluate efficacy." (PMID 35574401, 2022). "Prognostic factors for RFS in stage IB-IIIA primary lung adenocarcinoma differ by epidermal growth factor receptor mutation status." (PMID 36085020, 2022). "ARMS-PCR suggested intense expression of EGFR exon 19 del characterizes lung adenocarcinoma in patients with NP-MCP and is a potential risk factor for OLNM." (PMID 35912197, 2022). "We propose osimertinib is eligible for the treatment of SQ transformation from EGFR-mutated lung adenocarcinoma with T790M mutation." (PMID 35960133, 2022). "For example, mutations of KRAS and NRAS predict resistance to anti-EGFR antibodies in colorectal cancers, and patients with lung adenocarcinoma that harbor EGFR mutations or ALK rearrangements have shown remarkable efficacy in relevant targeted drug therapy." (PMID 36741696, 2022). "A previous cohort study estimated that 55.9% of advanced lung adenocarcinoma patients in eastern China have activating epidermal growth factor receptor (EGFR) mutations." (PMID 36556319, 2022). "In conclusion, this study demonstrated that the pre-treatment PET/CT-based radiomics features exhibited excellent performance for the prediction of EGFR mutation profiles in lung adenocarcinoma." (PMID 35800046, 2022). "Our previous studies have reported that human papillomavirus (HPV) infections and epidermal growth factor receptor (EGFR) expression are associated with a better survival prognosis in lung adenocarcinoma." (PMID 36358752, 2022). "Certain genetic factors are associated with the development of lung adenocarcinoma and the epidermal growth factor receptor (EGFR) and its mutation is probably the genetic risk factor of lung adenocarcinoma that has been studied most completely." (PMID 36011604, 2022). "Recent reports suggest similar brainstem lesions as a unique LM pattern, which occurs almost exclusively in patients with lung adenocarcinoma with EGFR mutation." (PMID 36320789, 2022). "This study aimed to evaluate the prognostic impact of the combination of epidermal growth factor receptor (EGFR) mutation and the presence of high-grade patterns (solid or micropapillary component) in resected stage I lung adenocarcinoma." (PMID 35266536, 2022). "Mutations in the epidermal growth factor receptor (EGFR) gene have been implicated in the incidence of lung adenocarcinoma." (PMID 36675990, 2022). "It was found that large population of the mutant tumor cells were present in the tissue specimens and EGFR mutation was primarily specific for lung adenocarcinoma." (PMID 35606799, 2022). "A total of 259 patients with stage IIIB–IV lung adenocarcinoma and actionable EGFR mutation who received first-line TKI treatment between 2008 and 2020 were retrospectively enrolled and analyzed." (PMID 35330404, 2022). "We report a case of stage IV lung adenocarcinoma with EGFR mutations that converted to squamous cell carcinoma due to long-term administration of EGFR-TKIs." (PMID 36158654, 2022). "Our previous work has demonstrated that hyperactivation of ERK2 is toxic to lung adenocarcinoma cells bearing KRAS or EGFR oncogenic mutations." (PMID 36418460, 2022). "Epidermal growth factor receptor (EGFR) is the most common mutation driving the carcinogenesis of lung adenocarcinoma (LUAD), with a mutation rate of up to 55% in Asian LUAD patients." (PMID 35847022, 2022).